PIK3CA (phosphatidylinositol-4,5-bisphosphate 3-kinase catalytic subunit alpha)
Diseases named in the same sentence as PIK3CA in open-access papers (continued):
Sharing a sentence is not in itself a finding about the gene and the disease.
cancer (continued). "In our study better responses to alpelisib were observed in pan-cancer but not BC cell lines and PDX with PIK3CA-mut/gain compared to -mut/neut, probably due to the limited sample size." (PMID 35181669, 2022). "Relatively non-toxic gene targeted therapies for PIK3CA and BRAF are FDA-approved or in advanced trials for some cancers." (PMID 31711466, 2019). "Currently, PIK3CA alterations are not regarded as agnostic targets, and the use of PI3K signaling cascade inhibitors is limited to hormone receptor-positive metastatic breast malignancies." (PMID 39596194, 2024). "Of note, while these eight PIK3CA NMD participants did not have any PIK3CA SNV detected in baseline ctDNA, they each had a detectable alteration in at least one of the 69 other cancer‐related genes evaluated on the F1L assay, suggesting that ctDNA was present in the blood of these participants." (PMID 36892268, 2023). "However, LPAR4 vs PIK3CA and LPAR4 vs PTEN were not related in either mutually exclusive or a co-occurring manner (p = 0.805 and p = 0.788, respectively) in pan-cancer cell lines." (PMID 31289610, 2019). "Interestingly, BRD9 is negatively correlated with PIK3CA; its correlation with KRAS is non-uniform, though it has been shown that BRD9 may mediate a PI3KCA-KRAS mutant oncogenic cancer phenotype." (PMID 34944438, 2021).
adenocarcinoma (93 papers, 2009 to 2026). A common cancer characterized by the presence of malignant glandular cells. "Alterations in the PI3K/AKT/mTOR pathway are prevalent, with PIK3CA mutations found in ~35% of adenocarcinomas and ~25% of squamous cancers." (PMID 41590369, 2026). "APC gene mutations are typically linked to the adenocarcinoma type of GC, while PIK3CA mutations involve the activation of the PI3K/Akt pathway, further promoting the growth and metastasis of cancer cells." (PMID 40861444, 2025). "Given that the majority of reports concerning mutated PIK3CA were conducted in adenocarcinoma, the clinicopathological meaning of PIK3CA mutations has rarely been documented in SCC, especially in cases with limited sample sizes." (PMID 38616230, 2024). "Nine years later, lung bilateral adenocarcinoma arose on PIK3CA mutated tissues supported by different clonal mutations." (PMID 37662840, 2023). "EGFR (Arg255Gln), EGFR (Ala647Thr), EGFR (Leu858Arg), KRAS (Gly12Cys), ALK (Pro254Thr), ALK (Trp288Ser), ALK (Glu797Lys), ROS (Glu1902Lys), PIK3CA (Met1043Ile), ROS (Leu567Val), and ROS (Phe1153Leu) mutations were present only in patients with adenocarcinoma." (PMID 36422072, 2022). "PIK3CA mutations were more common in the mucinous MSS cohort compared to the adenocarcinoma NOS MSS cohort (30.8% vs. 8.8% p < 0.05)." (PMID 32984045, 2020). "It’s reported there was an different distribution of PIK3CA mutations between adenocarcinoma and SCC histological subtypes of EC." (PMID 25106743, 2014). "A previous study showed an acquired PIK3CA mutation in SCLC transformed from EGFR-mutated adenocarcinoma after EGFR-TKI therapy." (PMID 24195468, 2013). "Analysis of PIK3CA exons 8, 9 and 20 demonstrated that 13 adenocarcinomas (7.0%) harboured mutations." (PMID 21473780, 2011). "Here, 20 adenocarcinomas (10 colorectal, two endometrial and 8 gastric) exhibited co-occurring PIK3CA and KRAS mutations." (PMID 19924296, 2009). "Because PIK3CA mutations favored non-adenocarcinoma histology only one PIK3CA mutant cell line was included." (PMID 19238210, 2009). "Interestingly in our study PIK3CA gene showed homozygous nucleotide substitutions in all mutated adenocarcinoma suggesting that major genetic alterations affected the locus 3q26.3, where the PIK3CA gene is located." (PMID 25220666, 2014). "Molecularly, G12V, and G12D are the most common KRAS mutations in mesonephric-like adenocarcinoma, and concurrent ARID1A and PIK3CA mutations are relatively common, with 1q copy number gain being the most common." (PMID 38444000, 2024). "We identified frequent CNVs of the ATRX and RB1 genes in NENs and key driver mutations of the ARID1A, PIK3CA, CTNNB1, and MYC genes in nNENs, especially adenocarcinomas." (PMID 34422662, 2021). "PIK3CA is overexpressed in ESCC compared to adenocarcinoma or normal esophagus in TCGA-ESCA dataset." (PMID 32974170, 2020).
adenocarcinoma (continued). "The distribution of PTEN, PIK3CA, BRAF and K-RAS mutations and loss of PTEN expression in the 186 adenocarcinomas available from EPIC Norfolk." (PMID 21473780, 2011). "In addition, a previous report has demonstrated that high microsatellite instability (MSI-high) and mutations in genes, such as KRAS, PIK3CA, and PTEN, are associated with rectal endometriosis-associated adenocarcinoma." (PMID 40065885, 2025). "It should be noted that those investigating the amplification of the PIK3CA gene in SCC or PIK3CA mutation in adenocarcinoma fall beyond the scope of this review and are not included in the discussion here." (PMID 38616230, 2024). "Further research should be performed to investigate whether there are differences in terms of PIK3CA mutation rates between SCC and adenocarcinoma." (PMID 38616230, 2024). "Unlike those on adenocarcinoma, for which there have been numerous reviews, reviews on mutated PIK3CA in SCC are scarce and have seldom been published." (PMID 38616230, 2024). "The most mutated immunophenotypes of adenocarcinomas were the undefined (1 KRAS; 2 PIK3CA, and 1 BRAF) and the biliopancreatic (2 KRAS and 1 BRAF), followed by the gynecological immunophenotype (1 case with concomitant KRAS and PDGFRA missense mutation and 1 with PIK3CA mutation)." (PMID 36346458, 2023). "With the progression of the disease, mutations of EGFR L858R, PIK3CA H1047R, and ERBB2 S310F were detected in punctured lumbar tissues, and EGFR L858R and PIK3CA H1047R in ctDNA, consistent with the pathological characteristics of adenocarcinoma." (PMID 32508051, 2020). "Additionally, we found that sample 6935 had co-occurring mutations in PI3K (PIK3CA) and RTK-RAS (BRAF) pathways, and the patient suffered a poorly differentiated adenocarcinoma in the ascending colon." (PMID 25617745, 2015). "PIK3CA mutation analysis of the second (adenocarcinoma) and third (SCLC) biopsy specimens was performed, but no mutation was detected from either sample." (PMID 24195468, 2013). "Furthermore, in our cohort, the presence of PIK3CA alterations was correlated with adenocarcinoma." (PMID 35330454, 2022). "KRAS-G12C and PIK3CA-Q546K were identified in 92.3% and 38.4% of 13 MAP adenocarcinomas, respectively." (PMID 42164324, 2026). "However, the role of mutated PIK3CA in adenocarcinoma has not been discussed." (PMID 38616230, 2024).
adenocarcinoma (continued). "Gene amplifications of 3q including SOX2, TP63, PIK3CA, and EPHB3 were observed in as many as 86% of SQC samples but only 21% of adenocarcinoma samples." (PMID 28591695, 2017). "A strong negative correlation was identified between adenocarcinoma and altered PIK3CA (r = −0.50918; p = 0.0029)." (PMID 35330454, 2022). "The correlation analysis indicated negative correlation between adenocarcinoma and altered PIK3CA (r = −0.50918; p = 0.0029)." (PMID 35330454, 2022). "For example, in our cohort, canonical oncodriver mutations were identified in three of the six tumors with an adenocarcinoma component (SOS1 in Pa34, EGFR/PIK3CA in Pa35, and KRAS/PIK3CA in Pa37) compared to pure LUADs, the majority of which harbor driver mutations." (PMID 34873156, 2021). "A greater percentage of the patients with PIK3CA amplifications had diffuse-type gastric cancer (52.9% vs. 38.7%, P=0.004) and poorly differentiated adenocarcinoma (60.7% vs. 48.4%, P=0.031) compared with those patients without PIK3CA amplifications." (PMID 26701847, 2016). "In a subgroup of non-smokers with adenocarcinoma, EGFR was the most frequently altered gene, with a mutation rate of 49.8%, followed by EML4-ALK (9.3%), PTEN (9.1%), PIK3CA (5.2%), c-Met (4.8%), KRAS (4.5%), STK11 (2.7%), and BRAF (1.9%)." (PMID 22768234, 2012). "The correlation analysis indicated a strong negative correlation between adenocarcinoma and altered PIK3CA, while a moderate correlation was noticed between time (days) to event (death) and former smokers (positive correlation) and never smokers (negative correlation)." (PMID 35330454, 2022). "Other examples of carcinogenic drivers for adenocarcinoma include modifications in protein kinase B (AKT), BRAF, human epidermal growth factor receptor-2 (HER2), phosphatidylinositol-4,5-bisphosphate 3-kinase catalytic subunit alpha (PIK3CA), MET, ROS1, RET, and KRAS." (PMID 35004079, 2022). "Similarly, PIK3CA true gene amplification was found in 12.8% of cases with SCC, while only 4 patients with non-squamous tumors were PIK3CA-amplified, including 3 adenocarcinomas and one pleomorphic carcinoma." (PMID 24736592, 2014). "Alterations in ‘typical’ adenocarcinoma key-driver genes—including APC, KRAS, NRAS, PIK3CA, PTEN, or SMAD4 —have not been detected so far." (PMID 35205133, 2022). "These mutations consisted of 19 KRAS (24.7%), 10 EGFR (13%), five BRAF (6.5%), four PIK3CA (5.2%), one HER2 (1.3%), one HER4 (2.2%) and none for HER3. mEGFR, mBRAF and mHER2 were present exclusively in adenocarcinomas while mKRAS were more frequent in adenocarcinoma and large cell histologies." (PMID 19238210, 2009).
breast (19 papers, 2008 to 2025). "Our results show that BRAF, KRAS and PIK3CA mutations occur prior to malignant transformation demonstrating that these oncogenic alterations are primary genetic events in colorectal carcinogenesis." (PMID 18782444, 2008). "Our present results indicated that hot spot activating PIK3CA and RAS mutations were biomarkers of cetuximab resistance among HNSCC patients in the first-line recurrence setting, as is also the case in colorectal cancer." (PMID 32296588, 2020). "Further larger studies and mechanistic investigation into the function of miR-520a/PIK3CA axis are warranted to advance the understanding of its role in colorectal carcinogenesis." (PMID 25834816, 2015). "In conclusion, our results show that mutations of BRAF, KRAS and PIK3CA occur in non-malignant lesions of colorectum demonstrating that these oncogenic alterations are primary genetic events in colorectal carcinogenesis." (PMID 18782444, 2008). "Surprisingly, the same FGFR3 but not PIK3CA point mutation was found in mBT liver metastasis." (PMID 33912469, 2021). "In addition, PIK3CA gene alteration was more frequently observed in lung SQCC than in ADC." (PMID 25384882, 2015).
infection (12 papers, 2011 to 2023). The state of being infected such as from the introduction of a foreign agent such as serum, vaccine, antigenic substance or organism. "Previous findings that other PIK3CA-targeting compounds inhibit infection by two different IAV strains support PIK3CA as a targetable node for IAV treatment." (PMID 37758692, 2023). "Next, normal mammary cells (MCF-10A and HMEC) were transduced with the PIK3CA- or PIK3R1-ReMB virus at a low multiplicity of infection (MOI = 0.3)." (PMID 29636477, 2018). "In accordance with these data, we found a significant association between copy number amplifications in PIK3CA and HPV 16/18 infection (p = 0.004)." (PMID 26087196, 2015). "This points to a rolefor PI3K in the regulation of ERα expression, but the cells in our model alreadyformed ERα + xenografts before infection with the PIK3CA vector." (PMID 25527189, 2014). "RT-qPCR showed that the expression of PIK3CA declined by ~50% after infection." (PMID 32732866, 2020). "The expression levels of ITGA1, ITGA5, FAK, PIK3R1, PIK3CA and AKT1 were significantly higher in the 1 MOI L. salivarius-treated group, than in untreated cells at 2, 8, and 16 h post-PEDV infection." (PMID 34957282, 2021). "In addition, the PI3K-Akt signaling pathway-related genes were expressed at lower levels in SFTSV infection 24 and 48 h, for example, GP1BA, PIK3CA, PIK3CB, AKT3, PRKG1, and PRKG2." (PMID 37211158, 2023). "In addition, genes related to PI3K-Akt signaling pathway showed downregulation and inhibition at 48 h post-infection, such as GP1BA, PIK3CA, AKT3, and PLA2G4A." (PMID 37211158, 2023). "Data revealed that the expression of Pik3cg (P = 4.0E-3; unpaired t-test) and Pik3cd (P = 7.4E-6; unpaired t-test) genes, but not Pik3ca, are upregulated in the heart tissue of T. cruzi-infected mice 18 days post infection (dpi)." (PMID 29666415, 2018). "Apart from IL-6 (miR-9 target), PIK3CA, and CAV1 (miR-124 target), no other target gene has been found to be reported previously either in a case of JEV infection or in infection by any other flaviviruses." (PMID 31578247, 2019).
genetic disorders (11 papers, 2019 to 2026). "PIK3CA-related overgrowth spectrum (PROS) comprises a group of rare genetic disorders caused by de novo, mosaic, postzygotic gain-of-function mutations in the PIK3CA gene." (PMID 42222744, 2026). "PIK3CA related disorders (PRD, OMIM: *171834) are genetic disorders resulting from pathogenic somatic mosaic variants in the PIK3CA gene, which encodes a protein crucial for regulating cell growth and division." (PMID 39872006, 2024). "Our case suggested an association and perhaps a causal link between the two different PIK3CA-related genetic diseases." (PMID 35154272, 2022). "This work illustrates the importance of allele dosage and expression when artificial systems are used to model human genetic disease caused by activating PIK3CA mutations." (PMID 33514588, 2021). "PIK3CA‐related overgrowth spectrum is a group of rare genetic disorders with asymmetric overgrowth caused by somatic mosaic PIK3CA mutations." (PMID 30919936, 2019). "Klippel–Trenanauy syndrome (KTS) is a rare genetic disease determined by overexpression of the phosphatidylinositol-4-5-bisphosphate 3 kinase catalytic subunit (PIK3CA) gene." (PMID 40729201, 2023).
hematologic malignancies (9 papers, 2017 to 2026). "CB-839 has been reported to be effective for several types of solid cancers and hematological malignancies and many clinical trials of CB-839, including targeting PIK3CA-mutated CRC (ClinicalTrials.gov identifier: NCT02861300), are ongoing." (PMID 32365457, 2020). "The PIK3CA signaling pathway is a drug target in treating several hematologic malignancies (Jabbour, Ottmann, Deininger, & Hochhaus, 2014)." (PMID 28035236, 2017). "Subgroup analysis showed the strongest effects in hematological malignancies (g = 0.85), particularly in studies targeting oncogenes such as KRAS, MYC, and PIK3CA." (PMID 41517680, 2026).
gastrointestinal tumors (7 papers, 2016 to 2025).